RN7SL364P (RNA, 7SL, cytoplasmic 364, pseudogene)
Gene: Miscellaneous RNA gene on chromosome 19 (46,688,797 to 46,689,068, reverse strand). Ensembl gene ENSG00000243560.
Homologues: Orthologues: chimpanzee Metazoa_SRP (99% identical), macaque Metazoa_SRP (88% identical). Paralogues in human: RN7SL1 (86% identical), RN7SL2 (86% identical), RN7SL3 (85% identical), RN7SL803P (83% identical), RN7SL91P (83% identical), RN7SL18P (82% identical), RN7SL230P (82% identical), RN7SL126P (81% identical), RN7SL118P (81% identical), RN7SL45P (81% identical), RN7SL493P (81% identical), RN7SL712P (81% identical), and 703 more.